CUX1 (cut like homeobox 1)
Diseases named in the same sentence as CUX1 in open-access papers (continued):
Sharing a sentence is not in itself a finding about the gene and the disease.
lung carcinoma (5 papers, 2016 to 2022). "Driver_plot visualizes supporting SV and CNV profile in the lung cancer sample for driver fusion gene “CUX1-RET”." (PMID 35113898, 2022). "Driver_object reports SV and CNV profile in the lung cancer sample responsible for the formation of driver fusion gene “CUX1-RET” in NSCLC." (PMID 35113898, 2022). "Driver_correlation_coefficient calculates the correlation coefficient of the input fusion gene “CUX1-RET” in the lung cancer sample." (PMID 35113898, 2022). "Driver_result reports the “CUX1-RET” fusion gene as a driver for the lung cancer sample." (PMID 35113898, 2022). "DriverFuse classifies the “CUX1-RET” fusion gene as a driver for the CCLE lung cancer sample." (PMID 35113898, 2022). "However, we found pathological mutations in the PTPN11, NF1, CUX1, IKZF1 gene and TERT promoter, which better fit a diagnosis of a melanoma than of lung cancer." (PMID 34819052, 2021). "In a previous report, we detected 15 RET fusion transcripts in cells taken from a lung cancer patient and confirmed five RET fusion partners (KIF5B, CCDC6, TRIM33, NCOA4, and CUX1)." (PMID 27150058, 2016).
adenoma (4 papers, 2014 to 2022). A neoplasm arising from the epithelium. "Importantly, while RAS alone caused the appearance of adenomas that exhibited hallmarks of cellular senescence, the combination of CUX1 and RAS produced higher grade adenomas which, in one case, evolved to the adenocarcinoma stage." (PMID 36176767, 2022). "While the KRASG12D mice developed solely grade 1 adenomas, mice expressing KRASG12D and CUX1 developed higher-grade adenomas and one large adenocarcinoma." (PMID 34204734, 2021). "Moreover, pathophysiological analysis of these tumors demonstrates that whereas the KRASG12V mice solely developed grade 1 adenomas (or adenomas with grade 1 nuclear atypia), mice expressing both CUX1 and KRASG12V developed higher grade adenomas (grades 1 and 2) and one large adenocarcinomas." (PMID 24618719, 2014).
autism spectrum disorder (4 papers, 2021 to 2025). A spectrum of developmental disorders that includes autism, and Asperger syndrome. "The down regulation of SatB2 and Cux1 are particularly interesting as abnormal expression of both are associated with altered behavior in mice and are suspected to be a contributor to autism spectrum disorder-like symptoms in humans." (PMID 40067832, 2025). "Recent work linked a mutation in a human accelerated region (HAR) that likely increases CUX1 expression to autism spectrum disorder, suggesting that human-derived changes in CUX1 expression alter human behavior." (PMID 36658652, 2023).
cervical cancer (4 papers, 2018 to 2023). A primary or metastatic malignant neoplasm involving the cervix. "This study also confirms that SLC2A1 and CA2 are highly expressed, and that CUX1 is weakly expressed, in cervical cancer tissues." (PMID 37042849, 2023). "Consistently, elevated levels of p200 CUX1 and its proteolytically processed isoform p110 were noted in these NB cells, cervical cancer HeLa cells, colon cancer LoVo cells, and prostate cancer PC‐3 cells, than those of non‐transformed normal MCF 10A cells." (PMID 31709724, 2019). "This study predicts that anti-CTLA-4 therapy may serve as an immunotherapeutic agent for managing cervical cancer and that the expression of CUX1, SLC2A1, and CA2 genes validated by clinical samples may serve as important targets for treatment modalities in cervical cancer." (PMID 37042849, 2023).
glioblastoma (4 papers, 2016 to 2022). The most malignant astrocytic tumor (WHO grade IV). "In glioblastomas, TCGA reveals that the chromosomal region including 7q22, where CUX1 resides, is the most frequently and highly amplified chromosomal region." (PMID 36176767, 2022). "TCGA and REMBRANDT data also show shorter survival of glioblastoma patients with high CUX1 mRNA expression." (PMID 36176767, 2022). "In glioblastoma cells, resistance to the mono-alkylating agent temozolomide was reduced by CUX1 knockdown but increased by ectopic expression of CUX1 or the two CUT domains." (PMID 36176767, 2022). "Elsewhere, we observed that CUX1 knockdown did not reduce the clonogenic efficiency of U251 glioblastoma cells and A549 lung cancer cells which exhibit low ROS levels." (PMID 34204734, 2021).
melanoma (4 papers, 2015 to 2021). A malignant, usually aggressive tumor composed of atypical, neoplastic melanocytes. "In keeping with our data, MECOM, MLL2 (KMT2D), MLL (KMT2A), ARID2, and CUX1 were among the most frequently mutated epigenetic genes in the TCGA and Broad Institute melanoma cohorts." (PMID 26221190, 2015). "TRIM24-BRAF and CUX1-BRAF fusions have previously been reported in melanoma." (PMID 33441414, 2021).
acute myeloid leukemia (3 papers, 2020 to 2022). Acute myeloid leukemia (AML) is a group of neoplasms arising from precursor cells committed to the myeloid cell-line differentiation. "Cut-like homeobox 1 (CUX1) is a haploinsufficient tumor suppressor commonly inactivated in acute myeloid leukemia and high-risk myelodysplasia." (PMID 33931647, 2021). "Furthermore, CUX1 was late identified as a haploinsufficient tumor suppressor in acute myeloid leukemia, because RNAi-mediated cut (the Drosophila ortholog of CUX1) knockdown led to the development of melanotic pseudotumors in a Drosophila tumor model." (PMID 32547943, 2020). "Given the relevance of CUX1 to myeloid malignancies, we first sought to identify the CUX1 isoforms expressed in human acute myeloid leukemia (AML) cells." (PMID 34997000, 2022).
bladder cancer (3 papers, 2016 to 2023). "CUX1 stimulates the transcription activity of PIK3CA in bladder cancer cells via direct interaction with the binding site of the PIK3CA promoter." (PMID 37627900, 2023). "According to literature research, this is the first study demonstrating that PIK3CA expression is positively correlated with CUX1 in bladder cancer cells." (PMID 33344221, 2020). "In summary, our study demonstrates for the first time that PIK3CA is overexpressed in bladder cancer, and is regulated by the transcription factor CUX1." (PMID 33344221, 2020). "Significantly, restoration of PIK3CA expression rescued bladder cancer cells from CUX1-knockdown inhibition of growth, aggressiveness, and angiogenesis." (PMID 33344221, 2020). "Trying to reveal the function of CUX1 in bladder cancer cells, we first transfected cell lines EJ and T24T with a CUX1-ovexpressing vector and verified the expression of CUX1 by qRT-PCR and Western blot." (PMID 33344221, 2020). "In contrast, our study claimed that the expression of PIK3CA is regulated by CUX1 in bladder cancer." (PMID 33344221, 2020). "The PIK3CA is overexpressed in bladder cancer and its expression is regulated by CUX1." (PMID 37627900, 2023). "CUX1 upregulates PIK3CA expression in bladder cancer and this in turn, further activates EMT." (PMID 37627900, 2023). "ChIP assay indicated that binding to the PIK3CA promoter could be increased or decreased with overexpression or knockdown of CUX1 in bladder cancer cells, respectively." (PMID 33344221, 2020). "This suggests that CUX1 may exert its tumor promoting function through transcriptional regulation of PIK3CA in bladder cancer." (PMID 33344221, 2020). "Moreover, dual-luciferase reporter assay demonstrated that up-regulation of CUX1 facilitated the transcription activity of PIK3CA in bladder cancer cells." (PMID 33344221, 2020). "It revealed same outcome like above that, PIK3CA knockdown weaken the proliferation, migration, invasion and angiogenesis capabilities of EJ and T24T cells, however restoration of CUX1 overexpression rescued bladder cancer cells from their defects resulted from knockdown of CUX1." (PMID 33344221, 2020). "However, the potential mechanism of CUX1 regulation of PIK3CA in bladder cancer cells requires further investigation." (PMID 33344221, 2020). "In summary, we determined that CUX1 is a vital TF of PIK3CA, regulating its expression and resulting changes in cellular functions in bladder cancer cells." (PMID 33344221, 2020). "Tissue microarray (TMA) with 66 bladder cancer patients was surveyed via immunohistochemistry to evaluate the level of PIK3CA and CUX1 and we found upregulation of PIK3CA in bladder cancer tissue and patients with higher level of PIK3CA presented with poorer prognosis." (PMID 33344221, 2020). "Interestingly, there are no literature reports of PIK3CA regulation by CUX1 in bladder cancer." (PMID 33344221, 2020).
breast tumors (3 papers, 2009 to 2022). "Lats1 mRNA steady-state level was increased approximately 3-fold in Hs578T breast tumor cells that were infected with the p110 CUX1 retroviral vector." (PMID 19656388, 2009). "Specifically in estrogen-receptor positive breast tumors cells, the up-regulation of KIFC1 is also related to a transcription factor p110 CUX1." (PMID 28977870, 2017).
Cognitive impairment (3 papers, 2022 to 2025). Abnormal cognition is characterized by deficits in thinking, reasoning, or remembering. "One aspect of this condition is that individuals with one functional CUX1 allele often close the developmental gap over time (i.e., cognitive impairments and delays disappear with age)." (PMID 36658652, 2023). "Heterozygous variants in CUX1 are associated with global developmental delay with or without intellectual impairment (OMIM 618330)." (PMID 40282419, 2025).
developmental delay (3 papers, 2023 to 2025). "The Cut Homeobox 1 (CUX1) gene has been implicated in a number of developmental processes and has recently emerged as an important cause of developmental delay and impaired intellectual development." (PMID 39103808, 2024). "Interestingly, the proportion of individuals affected by motor developmental delay was higher in those who harbored a CUX1 variant that affected both proteins (12/13, 92%) compared to individuals with a variant that affected only CUX1 (14/20, 70%)." (PMID 37644171, 2023). "Disease-causing variants in CUX1 lead to a non-specific phenotype with mild to moderate developmental delay/ID with possible developmental catch-up." (PMID 37644171, 2023).
leukemia (3 papers, 2021 to 2023). A malignant (clonal) hematologic disorder, involving hematopoietic stem cells and characterized by the presence of primitive or atypical myeloid or lymphoid cells in the bone marrow and the blood. "Here, in a genetically modified murine model, the authors show that CUX1 deficiency impairs apoptosis leading to leukemia when combined with mutant Flt3-ITD." (PMID 33931647, 2021). "Using a murine Cux1-deficient leukemia model and human cells, we establish that CUX1-deficient leukemia cells rely on elevated levels of CFLAR to evade apoptosis." (PMID 33931647, 2021). "Our study illuminates the molecular pathogenesis of CUX1-deficient leukemias and establishes that tumor suppressor gene haploinsufficiency can provoke collateral addiction to adaptive cellular pathways of potential therapeutic importance." (PMID 33931647, 2021). "In this study, we sought to identify genetic vulnerabilities in CUX1-deficient AML cells using CRISPR/Cas9 screening to assess whether CUX1 deficiency invokes adaptive cellular pathways critical for leukemia survival." (PMID 33931647, 2021). "Mechanistically, CUX1 deficiency directly alleviates CUX1 repression of the CFLAR promoter to drive CFLAR expression and leukemia survival." (PMID 33931647, 2021). "Having established that CFLAR depletion triggers apoptotic cell death in U937 and THP-1 myeloid cancer cell lines, we sought to test the relevance of our findings in our Cux1-haploinsufficient murine leukemia model." (PMID 33931647, 2021). "Long-term treatment of our Cux1-haploinsufficient leukemia model with birinapant will be interesting to determine the durability of responses." (PMID 33931647, 2021). "To assess whether leukemias were transplantable, we injected 2 × 105 bone marrow cells from two Cux1+/−;Flt3ITD mice diagnosed with AML or Flt3ITD mice along with the same number of wild-type bone marrow support cells into irradiated recipient wild-type mice." (PMID 33931647, 2021). "In order to investigate whether CUX1-deficient primary leukemic cells are more reliant on CFLAR, we sought to generate a CUX1-deficient leukemia model." (PMID 33931647, 2021).
prostate carcinoma (3 papers, 2019 to 2021). A carcinoma that arises from epithelial cells of the prostate gland. "In prostate cancer, the different CUX1 variants even seem to mediate antagonistic effects depending on cathepsin L activity: In androgen-sensitive tumors, cathepsin L is highly expressed and cleaves CUX1 into the tumor-promoting p110 isoform." (PMID 34070180, 2021). "We have demonstrated that CUX1 is differentially expressed in androgen-sensitive and androgen-independent prostate cancer cells." (PMID 32180898, 2020). "In public datasets, there was positive expression correlation between CUX1 and ENO1, GPI, or PGK1 in NB, colon cancer, or prostate cancer tissues, and their levels were associated with poor survival of tumor patients." (PMID 31709724, 2019). "In addition, circ‐CUX1 levels were positively correlated with those of CUX1 in tissues of NB (R = 0.590, P < 0.0001), colon cancer (R = 0.868, P < 0.0001), or prostate cancer (R = 0.619, P = 0.0023)." (PMID 31709724, 2019). "Notably, circ‐CUX1 levels were higher in tissues of NB, colon cancer, and prostate cancer, than normal fetal adrenal medulla or adjacent normal tissues." (PMID 31709724, 2019). "Thus, rather than a simple presence or absence of CUX1, the relative balance of CUX1 isoforms and their interplay may be a significant factor in the functional role of CUX1 in castrate resistant prostate cancer and may be an avenue for future work." (PMID 32180898, 2020). "Thus, rather than a simple presence or absence of CUX1, the relative balance of CUX1 isoforms and their interplay is a significant factor in the functional role of CUX1 in castrate resistant prostate cancer." (PMID 32180898, 2020).
B cell lymphoma (2 papers, 2020 to 2025). "Interestingly, CUX1 expression is also decreased in PRDM15-deficient B cell lymphoma models, where loss of PRDM15 impairs lymphomagenesis." (PMID 41282092, 2025).
Myelodysplasia (2 papers, 2021 to 2025). Clonal hematopoietic stem cell disorders characterized by dysplasia (ineffective production) in one or more hematopoietic cell lineages, leading to anemia and cytopenia. "The co-occurrence of two different myelodysplasia-associated somatic variants (CUX1/ETV6 and ASXL1/BCOR) was observed in 2 patients." (PMID 41188636, 2025). "Eight myelodysplasia-associated somatic variants in the BCOR/BCORL1, DNMT3A, ASXL1, CUX1, and ETV6 genes were found in 7 patients (5 AA and 2 MDS-h patients, 17%); neither AA patient had evidence of myelodysplasia at the time of analysis." (PMID 41188636, 2025).
myelodysplastic syndrome (2 papers, 2021 to 2023). A clonal hematopoietic disorder characterized by dysplasia and ineffective hematopoiesis in one or more of the hematopoietic cell lines. "Additionally, genetic abnormalities within CUX1 have been linked to polycystic kidney disease and myelodysplastic syndrome in mouse models." (PMID 33933144, 2021).
myeloid leukemia (2 papers, 2009 to 2021). A clonal proliferation of myeloid cells and their precursors in the bone marrow, peripheral blood, and spleen. "In mixed genetic backgrounds, many virgin p75 CUX1 mice succumbed to myeloproliferative-disease (MPD)-like myeloid leukemias." (PMID 19656388, 2009).
ovarian carcinoma (2 papers, 2020 to 2024). A malignant neoplasm originating from the surface ovarian epithelium. "The expression levels of VPS13B, TBC1D22A, PPP3CA, CUX1, and PPP1R15A genes were found to be up-regulated in ovarian tissue of cisplatin-resistant ovarian cancer patients compared to those with ovarian cancer." (PMID 39103807, 2024). "VPS13B, TBC1D22A, PPP3CA, CUX1 and PPP1R15A were identified as poor prognostic genes for cisplatin resistance in ovarian cancer, while PLGRKT, CDKAL1 and TAP1 were identified as good prognostic genes." (PMID 39103807, 2024). "VPS13B, TBC1D22A, PPP3CA, CUX1 and PPP1R15A were identified as poor prognostic genes of cisplatin resistance in ovarian cancer, while PLGRKT, CDKAL1 and TAP1 were identified as good prognostic genes." (PMID 39103807, 2024). "Through biological information screening, RT-qPCR and WB verification, it was found that VPS13B, TBC1D22A, PPP3CA, CUX1 and PPP1R15A were highly expressed in cisplatin-resistant tissues of ovarian cancer, while PLGRKT, CDKAL1 and TAP1 were low expressed." (PMID 39103807, 2024).
pancreatic neuroendocrine neoplasm (2 papers, 2017 to 2018). A neoplasm with neuroendocrine differentiation that arises from the pancreas. "Among the branch genes differentiating the T1-3 cluster and T4-6 cluster in M9, CUX1 is a known oncogene and can make a tumor aggressive in pancreatic neuroendocrine neoplasm." (PMID 29050228, 2017).
schizophrenia (2 papers, 2020 to 2023). A major psychotic disorder characterized by abnormalities in the perception or expression of reality. "In neurons expressing the cortical layer III marker CUX1, there was a significant reduction in dendritic spine density in neurons from schizophrenia iPSCs compared to neurons from healthy control iPSCs." (PMID 37507766, 2023). "Cortical neurons expressing layer III marker CUX1, but not those expressing layer V marker CTIP2, showed significant reduction in dendritic spine density in schizophrenia, mirroring findings in postmortem studies." (PMID 37507766, 2023).
temporal lobe epilepsy (2 papers, 2022 to 2023). A localization-related (focal) form of epilepsy characterized by recurrent seizures that arise from foci within the temporal lobe, most commonly from its mesial aspect. "Another study found multiple CUX2 and CASP (CUX1 alternatively spliced product, an alternative CUX1 isoform) variants in patients with temporal lobe epilepsy." (PMID 37744879, 2023).
triple-negative breast carcinoma (2 papers, 2019 to 2021). An invasive breast carcinoma which is negative for expression of estrogen receptor (ER), progesterone receptor (PR), and human epidermal growth factor receptor 2 (HER2). "Recently, active CUX1 has been shown to be upregulated in triple-negative breast cancer, and upon knockdown of CUX1, there was increased estrogen receptor ERα and drug sensitivity." (PMID 34439480, 2021).
alcohol addiction (1 paper, 2025). "Nek3, Ntf3, Cux1, and Irf6 expression changes were shared across at least three tissues and may be potential biomarkers of alcohol addiction." (PMID 41153338, 2025).
Alzheimer disease (1 paper, 2025). A progressive, neurodegenerative disease characterized by loss of function and death of nerve cells in several areas of the brain leading to loss of cognitive function such as memory and language. "We further stained for CUX1 as a marker of layer II/III neurons which can be vulnerable to TDP-43 pathology in FTD and degeneration in Alzheimer’s disease." (PMID 40149017, 2025).
anemia (1 paper, 2021). A reduction in the number of red blood cells, the amount of hemoglobin, and/or the volume of packed red blood cells. "Concurrent Cux1 haploinsufficiency and Flt3ITD mutation led to reduced frequency of stage II-IV progenitors compared with other groups, consistent with the anemia observed in these mice and alluding a very early defect in erythropoiesis." (PMID 33931647, 2021). "The changes in GMP and MEP numbers provide potential explanations for anemia and dominant myelopoiesis observed in Cux1+/−;Flt3ITD mice." (PMID 33931647, 2021). "Blood count analysis at necropsy revealed anemia and leukocytosis with the latter attributable to increased neutrophils, monocyte and blasts in mice transplanted with Cux1+/−;Flt3ITD cells, but not Flt3ITD cells." (PMID 33931647, 2021).